POM121L12 (POM121 transmembrane nucleoporin like 12)
Synonyms: DKFZp564N2472
Tractability: No criterion of Open Targets' tractability assessment is met for any kind of drug.
Gene: Protein-coding gene on chromosome 7 (53,035,633 to 53,036,925, forward strand). Ensembl gene ENSG00000221900.
Genetic constraint (gnomAD): Missense variants: 553 observed, 419.92 expected, observed/expected ratio (o/e) 1.32, 90% interval 1.23 to 1.41. Synonymous variants: 251 observed, 183.76 expected, observed/expected ratio (o/e) 1.37, 90% interval 1.23 to 1.52.
Homologues: Orthologues: chimpanzee POM121L12 (96% identical), mouse Pom121l12 (32% identical), rat Pom121l12 (32% identical), zebrafish pom121 (20% identical), tropical clawed frog pom121 (14% identical), Drosophila melanogaster Nup153 (8% identical). Paralogues in human: POM121L2 (34% identical), POM121 (25% identical), POM121C (18% identical), NUP214 (15% identical), NPAP1 (14% identical), NUP153 (10% identical).
Diseases named in the same sentence as POM121L12 in open-access papers:
POM121L12 is named in the same sentence as 2 diseases in open-access papers, as found by Europe PMC text mining. Sharing a sentence is not in itself a finding about the gene and the disease. The quoted sentences say what the papers report.
tumor (1 paper, 2020). "Conversely, one tumor pair shared missense mutations in three genes (EMSY, SMAD4, and POM121L12) and gene copy number amplification of three genes (SDHA, TERT, and EGFR)." (PMID 33139840, 2020).
POM121L12 also shares sentences with these, for which no sentence is quoted: cancer (1 paper).